CLCN2 (chloride voltage-gated channel 2)
Diseases named in the same sentence as CLCN2 in open-access papers (continued):
Sharing a sentence is not in itself a finding about the gene and the disease.
familial hyperaldosteronism (6 papers, 2019 to 2024). "Germline mutations in CLCN2, encoding the voltage-dependent chloride channel protein ClC-2, were identified in familial hyperaldosteronism (FH) type II, while another somatic mutation in CLCN2 was reported in a sporadic uPA." (PMID 35757409, 2022). "Genetic causes of familial hyperaldosteronism have been expanded through the report of germline pathogenic variants in KCNJ5, CACNA1H and CLCN2 genes." (PMID 35813615, 2022). "Rare germline variants of CYP11B2 (encoding aldosterone synthase), CLCN2 (encoding voltage-gated chloride channel ClC-2), KCNJ5, CACNA1H (encoding a subunit of T-type voltage-gated calcium channel CaV3.2), and CACNA1D have been reported in different subtypes of familial hyperaldosteronism." (PMID 31695023, 2019).
hyperaldosteronism (5 papers, 2019 to 2025). Overproduction of aldosterone by the adrenal glands, which may lead to hypokalemia and/or hypernatremia. "Genetic analysis of patients with hyperaldosteronism recently revealed CLCN2 missense mutations in regions known to affect ClC-2 gating." (PMID 33187987, 2021).
Azoospermia (4 papers, 2021 to 2025). Absence of any measurable level of sperm,whereby spermatozoa cannot be observed even after centrifugation of the semen pellet. "We consider CLCN2 c.607G > T pathogenic because of the neuroradiological and clinical findings, including azoospermia." (PMID 36879630, 2023). "Disruption of Clcn2 causes azoospermia, whereas loss of Lrrc8a results in abnormal, immotile spermatozoa." (PMID 33187987, 2021). "Male Clcn2−/− mice are infertile owing to early postnatal testicular degeneration and the ensuing azoospermia." (PMID 33187987, 2021).
cystic fibrosis (4 papers, 2004 to 2015). Autosomal recessive disorder caused by pathogenic variants in the CFTR gene (cystic fibrosis transmembrane conductance regulator), which encodes a chloride and bicarbonate channel expressed in epithelial cells, and follow the diagnosis criteria. "Several polymorphisms of key regulatory domains of CLCN2 were identified in a cohort of subjects with cystic fibrosis, who carry the same CF genotype." (PMID 15507145, 2004). "Possibly, in Cystic fibrosis different mutations could alter the functional interaction of the CFTR_HUMAN protein with the DERL1_HUMAN, RNF5_HUMAN, AHSA1_HUMAN and GOPC_HUMAN proteins, or between the CHIP_HUMAN and HSP7C_HUMAN or CLCN2_HUMAN proteins." (PMID 26046679, 2015). "Therefore, any therapeutic upregulation of ClCN2 in cystic fibrosis should deplete apical ENaCγ, thereby tempering sodium regulation, a desirable outcome in CF airways disease." (PMID 25626868, 2015). "However, Clcn2−/− mice do not suffer from lung disease, and additional ClC-2 knock-out in CFTR−/− mice did not deteriorate the phenotype of cystic fibrosis these animals." (PMID 25339907, 2014).
familial hyperaldosteronism type II (4 papers, 2018 to 2025). Familial hyperaldosteronism type II (FH-II) is a heritable form of primary aldosteronism (PA) characterized by hypertension of varying severity, and non glucocticoid remediable hyperaldosteronism. "Initially, CLCN2 mutations were identified in familial hyperaldosteronism type II (FH-II), where they led to increased chloride permeability, membrane depolarization, and the aberrant activation of voltage-gated calcium channels, ultimately stimulating aldosterone synthesis." (PMID 40725432, 2025).
idiopathic generalized epilepsies (4 papers, 2013 to 2021). "Heterozygous loss of function in CLCN2 mutations with pathogenic variants have been implicated previously in idiopathic generalized epilepsies." (PMID 34816733, 2021). "Currently, studies on mutations of CLCN2 gene investigate brain white matter edema, secondary paroxysmal kinesigenic dyskinesia, idiopathic generalized epilepsy and other diseases." (PMID 35011147, 2021). "Intriguingly, a genome search for susceptibility loci of common idiopathic generalized epilepsy identified a locus at 3q26 in the vicinity of the human CLCN2 gene." (PMID 24378849, 2013). "Certain homozygous or heterozygous CLCN2 mutations can cause two distinct phenotypes: leukoencephalopathy with ataxia (CLCN2; MIM#615651) and idiopathic generalized epilepsy (CLCN2; MIM#607628) including juvenile myoclonic epilepsy and juvenile absence epilepsy." (PMID 33343406, 2020).
primary aldosteronism (3 papers, 2018 to 2025). An endocrine disorder characterized by excessive production of aldosterone by the adrenal glands. "The P48R germline variant in CLCN2 has been rarely reported inindividuals with primary aldosteronism; our study is the first to report an association of asomatic P48R variant with APA." (PMID 41196931, 2025). "In the original family with FH type II, eight individuals were carriers of the CLCN2 mutation (resulting in the CIC-2 p.Arg172Gln substitution) and of these, seven tested positive with a screening test for primary aldosteronism (elevated aldosterone-to-renin ratio)." (PMID 29642543, 2018).
Constipation (2 papers, 2016 to 2025). Infrequent or difficult evacuation of feces. "Our results provide the first evidence that C3 deficiency can be considered to be a cause for the upregulation of CLCN2, unlike their levels in Lop-induced constipation." (PMID 41011160, 2025).
Leukoencephalopathy with ataxia (2 papers, 2020 to 2023). "Homozygous or compound heterozygous mutations in CLCN2 are known causes of Leukoencephalopathy with ataxia (CLCN2-related leukoencephalopathy; MIM615651), a rare autosomal recessive disease that has so far been reported in 18 individuals." (PMID 36879630, 2023).
lung carcinoma (2 papers, 2017 to 2022). "In this in vivo experiment a miR150 inhibitor was delivered intravenously using CLCN2 to treat H1299 human lung cancer xenografts." (PMID 28637023, 2017). "Tree injections of CLCN2/ miR150 inhibitor were intravenous administrated to H1299 human lung cancer xenografts at the miR150 inhibitor dose of 1.5 mg/Kg." (PMID 28637023, 2017). "Additionally, CLCN2 has been found to predict the development and occurrence of lung cancer and might serve as a novel molecular therapeutic target of non-small cell lung cancer." (PMID 36246902, 2022).
psychosis (2 papers, 2022 to 2024). "Through this pilot effort, we underscored the chloride voltage-gated channel 2 (CLCN2) gene as a possible druggable candidate for early-stage psychosis." (PMID 36967982, 2022). "Through these efforts, we now highlight chloride voltage-gated channel 2 (CLCN2) as a promising target for a specific dimension of cognition in early-stage psychosis, further supporting the utility of ONCs as a tool for the “druggable genome” approach in translational psychiatry." (PMID 36967982, 2022). "Although it is the largest case series of CLCN2-related LKPAT to date, the number of patients is still too small to draw any genotype–phenotype correlations and to ascertain that some findings, such as ASD and psychosis, are definitely linked to the disease and are not a co-occurrence." (PMID 38173802, 2024).
retinal degeneration (2 papers, 2013 to 2015). Degeneration of the retina. "The mutation localized to a region on chromosome 16 containing the CLCN2 gene is associated with retinal degeneration." (PMID 24378849, 2013). "ClC2-deficient (Clcn2-/-) mice display an early, severe retinal degeneration that results in almost complete blindness from birth on and the selective absence of vacuolation in their optic nerves suggests that the alterations of oligodendrocytes depend upon neuronal activity." (PMID 25763823, 2015).
colitis (1 paper, 2019). Inflammation of the colon. "Additionally, in a Chloride channel protein-2 (CIC-2; CLCN2) null mouse model, recovery from DSS-induced colitis was impaired and the epithelial permeability was decreased." (PMID 31195621, 2019).
developmental delay (1 paper, 2024). "Our findings expand the phenotypic spectrum of CLCN2-related leucoencephalopathy by adding prominent seizures, severe spastic paraplegia and developmental delay." (PMID 38173802, 2024).
Dravet syndrome (1 paper, 2019).
Epileptic encephalopathy (1 paper, 2015). A condition in which epileptiform abnormalities are believed to contribute to the progressive disturbance in cerebral function. "Furthermore, variations in CLCN1, CLCN2, and CLCN4 have been reported in patients with idiopathic epilepsy and epileptic encephalopathy; however, the association of some variants with disease pathogenesis is still controversial." (PMID 25794116, 2015).
heart failure (1 paper, 2015). Inability of the heart to pump blood at an adequate rate to meet tissue metabolic requirements. "mRNAs for ANP, CLCN2 and Navβ1 were increased with heart failure in all regions, while mRNAs for Cx43 and HCN1 were decreased." (PMID 26509807, 2015). "mRNA abundance for ANP, CLCN2 and Navβ1 was increased with heart failure; Nav1.1 was increased in the inferior nodal extension/compact node area." (PMID 26509807, 2015).
hepatocellular carcinoma (1 paper, 2022). A malignant tumor that arises from hepatocytes. "Additional research evidence indicated that CLCN2 was significantly up-regulated and could function as a prognostic factor in hepatocellular carcinoma." (PMID 36246902, 2022).
Hypokalemia (1 paper, 2019). An abnormally decreased potassium concentration in the blood. "Clcn2op/op mice displayed hypokalemia, a frequent abnormality in PA patients including several of those with CLCN2 mutations." (PMID 31615979, 2019).
megalencephalic leukoencephalopathy with subcortical cysts (1 paper, 2025). "In the mouse nervous system, HEPACAM (Hepatic And Glial Cell Adhesion Molecule, also known as GlialCAM) and MLC1 (Megalencephalic Leukoencephalopathy With Subcortical Cysts 1) stabilize CLCN2 in the plasma membrane by reducing its turnover rate and improving CLCN2 gating." (PMID 40140900, 2025).
Nephropathy (1 paper, 2023). A nonspecific term referring to disease or damage of the kidneys. "Eight heterozygous variants were identified in nephropathy-associated genes (CLCN2, C5orf42, GSN, LMX1B, CEP164, PKD1, ITGB4, and KANK2), but each could be discounted having been inherited from an unaffected parent." (PMID 37148394, 2023).
tic disorder (1 paper, 2020). Disorders characterized by recurrent TICS that may interfere with speech and other activities. "Subsequently, a validation study was performed to assess the association of CLCN2 G161S with tic disorder in an independent population." (PMID 33343406, 2020). "CLCN2 G161S was genotyped in 207 sporadic patients with tic disorder including 111 patients with GTS and 489 healthy controls." (PMID 33343406, 2020). "We genotyped CLCN2 G161S in 489 healthy controls and 207 sporadic patients with tic disorders including 111 GTS patients." (PMID 33343406, 2020).
Tremor (1 paper, 2023). An unintentional, oscillating to-and-fro muscle movement about a joint axis. "Changes in the expression of Parv, Calb, and CLCN2 in the cerebellum could be associated with clinical signs, such as tremor and uncoordinated gait, observed in mice infected with ZIKV." (PMID 37631975, 2023).
neurological disorders (3 papers, 2009 to 2025). "We screened the CLCN2 gene for its relevance to neurodevelopmental disorders and found that CLCN2 has been strongly implicated in neurological disorders." (PMID 33343406, 2020).
retinopathy (2 papers, 2023 to 2025). "Interestingly, in the case of CLCN2-associated retinopathy, comparative analysis of patient-derived RPE and ROs indicated that RPE dysfunction, rather than photoreceptor degeneration, was the primary causative factor." (PMID 39422807, 2025).
tumor (2 papers, 2017 to 2020). "On the basis of these experimental findings, the formulation CLCN2 was conjugated to the tumor suppressor microRNA, miR150 inhibitor and its therapeutic efficacy was evaluated in vivo." (PMID 28637023, 2017). "The tumor growth rate of the CLCN2-miR150 group was significantly lower than that of the control group (1.9% vs 18.0%, p<0.05)." (PMID 28637023, 2017). "Supporting this, KCNQ1, CFTR and ClCN-2 have been described as tumor suppressors in CRC." (PMID 33117152, 2020). "CLCN2 were able to efficiently deliver the miR150 inhibitor which resulted in decrease of tumor growth rate as compared to the no treatment control group." (PMID 28637023, 2017).
cancer (1 paper, 2022). A tumor composed of atypical neoplastic, often pleomorphic cells that invade other tissues. "Enrichment analysis on cancer-related pathways and processes correlated to our signature indicated that alteration of CLCN2 or CLCN6 expression could affect cell volume based on biological regulation and assembly of genetic material." (PMID 36246902, 2022). "Studies have revealed that CLCN2 and CLCN6 could participate in the regulation of various energy metabolism and other cancer biology." (PMID 36246902, 2022).
genetic diseases (1 paper, 2024). "Understanding the components of the ion and water homeostatic pathways might lead to strategies aimed at controlling or reversing myelinic oedema for the treatment of CLCN2-related leucoencephalopathy and related genetic diseases." (PMID 38173802, 2024).
CLCN2 also shares sentences with these, for which no sentence is quoted: male infertility (3 papers); cerebellar ataxia (2); familial hyperaldosteronism type I (2); Gilles de la Tourette Syndrome (2); neurodevelopmental disorder (2); adenoma (1); adrenal hyperplasia (1); adrenocortical tumors (1); Alzheimer disease (1); atrial fibrillation (1); Blindness (1); cardiac disease (1); Cognitive impairment (1); depression (1); Distichiasis (1); epilepsy syndrome (1); Gordon Holmes syndrome (1); HCMV infection (1); Hyperkalemia (1); Hypertension (1); inflammation (1); Intellectual disability (1); juvenile absence epilepsy (1); Kaya-Barakat-Masson syndrome (1); Krabbe disease (1); Lesch-Nyhan syndrome (1); lung disease (1); malaria (1); megalencephalic leukoencephalopathy (1); Menkes disease (1).
A further 20 diseases each share a sentence with CLCN2 in 1 paper.